IRF1 (interferon regulatory factor 1)
Diseases named in the same sentence as IRF1 in open-access papers (continued):
Sharing a sentence is not in itself a finding about the gene and the disease.
infection (continued). "Because IFNγ signaling significantly increases MHC-II expression via the IRF-1/CIITA axis, with peak serum IFNγ levels observed at 16 days post-MHV68 infection, the expression of MHC-II by germinal center B cells was measured next." (PMID 41263556, 2025). "IF staining of mouse brains at day 7 post-infection showed that the levels of p-STAT1, IRF1, and PD-L1 in Ifnar1−/− and Ifngr1−/− mice were lower than those in control littermates." (PMID 38715061, 2024). "In summary, these results demonstrated that infection with a virulent CSFV Shimen strain can induce the expressions of TRAF1, RIG-I, MAVS, IRF1, and ISG15." (PMID 38995016, 2024). "Similar to previous reports, the expression levels of IFIT1, IRF1, and MX1 in Znfx1–/– BMDMs were higher than those in WT BMDMs following H37Rv infection, despite the increased intracellular M. tuberculosis burden in Znfx1–/– BMDMs." (PMID 38016036, 2024). "Primary human Sertoli cells infected with either 5 or 10 MOI of the Zika virus showed a prominent, dose dependant, increase in the expression of ISGs including ISG15, OAS1, IRF1, and IFI6 48 hours post-infection, compared to uninfected controls at 8 hours." (PMID 39621805, 2024). "In contrast, in the current study with LmCen–/– infection, the expression of both IRF1 and IRF8 showed more reduction than LmWT infection." (PMID 39702382, 2024). "IRF-1 functions downstream of IFN expression, participating in the signal transduction pathway initiated by IFN during infection." (PMID 39850894, 2024). "WB analysis of mouse brains revealed higher levels of p-STAT1, IRF1, and PD-L1 in the brainstem of ECM mice, which increased with infection time." (PMID 38715061, 2024). "For OC43 infection, knockdown of IRF1 or IRF3 promoted viral protein synthesis compared to siRNA controls at both 2 and 3 days after infection." (PMID 37197656, 2023). "First, the expressions of IRF1, IRF3 and IRF7 were confirmed and then the expression levels of the ISGs before infection were analyzed." (PMID 37197656, 2023). "In 3D enteroids, the phagocyte chemoattractant genes, IL8 (CXCLi1) and IL8L (CXCLi2) and transcription factors, IRF1 and IRF7, were induced by STm infection." (PMID 37854334, 2023). "Together, these data suggest that IRF1 contributes to ZBP1-mediated PANoptosis in response to stimulation with IFNγ plus KPT-330 and infection with IAV by regulating ZBP1 expression." (PMID 37557956, 2023). "The expression of IRF1 and IRF7 was increased at 3 and 4 days after infection compared to uninfected controls." (PMID 37197656, 2023). "IRF1, an ISG itself, is upregulated during infection and has shown to have antiviral efficacy against MARV/EBOV, IAV, PRV3M, and MERS-CoV (though only limited comparisons to human IRF1 are available)." (PMID 37661999, 2023). "While the regulators NLRC5, IRF1, STAT1, and HLA-B were progressively activated through the infection time course in B.6 and B.1.1.8 infections, they were hardly detected in Delta infection." (PMID 36073824, 2022). "However, the fact that critical immune regulator genes, including IFN-β and IRF1, are read through in virus-infected cells demonstrates that viruses can dampen the host antiviral response via manipulation of 3 ́-end processing to ensure successful infection of the host cell." (PMID 35222412, 2022). "In this study, we examined the regulatory roles of IRF1, IRF7, and IFN-β in DTMUV replication and the expression profiles of infection-induced genes by constructing two knockout cell lines, KO IRF7 and KO IFNAR1, using CRISPR/Cas9 technology." (PMID 35891486, 2022). "We found cytokines like IFNγ, IL-4, IL-13, IFNβ1, TNFα, and transcriptional regulators such as HIF1α, STAT1, CTCF, TP73, IRF1, MXD1, ATF4, SPI1 mediate macrophage activation upon infection." (PMID 35789215, 2022). "We observed that IRF1 and IFNγ both strongly induced the expression of RARRES3 which led us to question if infection restriction by IRF1 was due to the induction of RARRES3 expression." (PMID 34871166, 2021).
infection (continued). "In HIV infections IRF1 appears to have a dual role: HIV initially upregulates IRF1 in order to initiate HIV replication, but at later stages of infection, HIV inhibits IRF1 functions, thereby evading the IRF1-mediated induction of antiviral responses." (PMID 34248923, 2021). "However, loss of RARRES3 did not impact IRF1-mediated restriction of infection." (PMID 34871166, 2021). "As for the two tested DNA viruses, HSV-1 was less affected by overexpression of the IRFs; only IRF1 and IRF7 decreased replication at 48 h post infection, with IRF7 catching up with the empty vector controls 56 h post infection." (PMID 34685580, 2021). "Several restriction factors (IRF1, MX1, STAT1, C18orf25) known to limit lytic infection were expressed at lower levels in the lytic subcluster." (PMID 33914843, 2021). "Transcription factors selected as biomarkers for targeting should be predicted for genes such as TLR7, TLR9, RHOA, IRF1, and IL6 since they are activated early in infection." (PMID 32872640, 2020). "Gene expression analyses demonstrated that IRF1 and IFN-β were expressed downstream of TLR4 after infection." (PMID 32210480, 2020). "After the IRF1-knockdown 293T cells and DF1-viperin-KO were infected with DTMUV, culture media and total cells were collected at indicated time pints post-infection." (PMID 32983049, 2020). "Our studies suggest that in dDCs, IRF7 is primarily activated following infection with CCHFV, whereas in LCs, IRF1 activation is primarily increased." (PMID 30036960, 2018). "However, some genes are down-regulated after stimulation, including IRF-1, a pivotal factor in the regulation of NK cells during infection, inflammation and metastasis, while PTGS2 is also down-regulated in NK cells, which could be favorable for NK function in SS." (PMID 29190907, 2017). "In addition increased levels of Ip10, Irf1, Stat1, Icsbp, at day 1 post infection in the blood of Ifnar1-/- as compared to the WT mice is in keeping with type I IFN inhibition of Th1 responses and could explain the subsequent reduction in bacterial load in the Ifnar1-/- infected mice." (PMID 26918359, 2016). "For example, different strains of S. aureus can activate different pattern recognition receptor (PRR) signaling cascades, specifically NOD2/IRF5 versus TLR9/IRF1, leading to different type I IFN responses that affect survival after infection." (PMID 27143388, 2016). "In HIV-infected Jurkat T cells beginning 24 h postinfection, IRF-1 expression was substantially decreased (lanes 4 to 6 versus lanes 1 to 3), while HDM2 expression increased during the course of infection." (PMID 27795392, 2016). "IRF-1 is downregulated and K48 polyubiquitinated in HIV-1-infected Jurkat T cells and during HIV-1 de novo infection of human primary CD4+ T cells." (PMID 27795392, 2016). "The expression of p21WAF/CIP1 was dramatically downregulated with time after infection, whereas expression of CDK2, a gene negatively regulated by IRF-1, was increased more than 2-fold." (PMID 27795392, 2016). "It is possible that infection with FV1 lpg1− reduces the amount of IRF8, which in turn inhibits the capacity of other transcription factors, such as IRF1, to form heterodimeric complexes that bind the IL12B promoter." (PMID 26630499, 2015). "Pattern "Virulent", in contrast, includes 1,165 genes whose expression levels were less strongly changed after infection with heat-inactivated MTB H37Rv or the attenuated vaccine strain BCG compared to the other bacteria (e.g. IL1R1, IRF1, PILRB)." (PMID 26586179, 2015). "To dissect the different roles of type I IFN and IRF-1 in the brain during VSV infection, we determined IFN-β mRNA in the brain parts after intranasal infection with VSV." (PMID 24675692, 2014). "A similar time-course experiment showed that IRF1 was up-regulated within 1 h after exposure of HeLa cells to HSV-1, reaching its maximum expression at 4 h post-infection." (PMID 25461762, 2014).
infection (continued). "Others have demonstrated an age-related decrease in IFN response through STAT1, IRF1 and IRF7 signaling following infection with West Nile Virus." (PMID 23936572, 2013). "Like the U937 cells, expression of the ISG, IRF-1, was also increased in NB4 cells exposed to ATRA alone but was higher in cells exposed to MuV + ATRA infection." (PMID 24225020, 2013). "Once infection is established, HIV-1 subverts the IRF1 response enabling viral replication and evasion of the host immune response." (PMID 23799084, 2013). "This suggests that the inhibition of the NF-κB response and of the transcription of several RelAp43 dependant genes (HIAP1, IRF1 and IFN-β) is critical for the success of the infection and the hence pathogenicity of lyssaviruses." (PMID 23271966, 2012). "Within IRF-1-/- mice we observed an increase in the percentage and number of WNV-specific CD8+ T cells at the peak of infection due to increased proliferation." (PMID 21909274, 2011). "One hour after infection, WNV-primed wild type or IRF-1-/- CD8+ T cells were added at an effector to target (E∶T) ratio of ten to one." (PMID 21909274, 2011). "Neither IFN treatment nor ISG induction eliminated infection, but IRF1, an antiviral transcription factor not suppressed by RSV, remained robustly expressed." (PMID 42319946, 2026). "Among them, we wanted to analyze the expression of interferon α and β, IFITM3, ISG15, MyD88, and IRF1 in DF-1 and DSK cells upon MVA infection and verify whether their expression is affected when STING functionality is impaired." (PMID 40981440, 2025). "Notably, TLR signaling genes interferon regulatory factor 1 (IRF1) and MyD88 are significantly induced by MVA infection in DSK cells, probably to counterbalance the reduced IFN-I response of the cytosolic DNA-sensing cGAS/STING/IRF3 axis." (PMID 40981440, 2025). "Findings from another study indicate IRF1−/− mice as highly vulnerable to infection with West Nile virus, which in turn pinpoints to effects in macrophages, whereas fibroblasts depleted of IRF1 were not affected by West Nile virus." (PMID 39773901, 2025). "To clarify how IRFs demonstrate different antiviral effects against human coronavirus infection, we investigate expression levels of antiviral genes in cells transfected with control pcDNA3, IRF1-pcDNA3, IRF3-pcDNA3 or IRF7-pcDNA3 at 24 hours after infection of 229E or OC43." (PMID 37197656, 2023). "As we analyze the TFs that belongs to each time of infection evaluated, we found that at 24-hpi, more than half of TFs are related to an M1 phenotype in humans and mouse, and also were upregulated in our results, corresponding to ARID3A, IRF1, MXD4, and BNC1." (PMID 38162669, 2023). "Critically, targets of transcription factors known to regulate inflammation (IRF1, STAT1, STAT3) and fibrosis (SMAD2/3, EGR1, TEAD4, YAP1) appeared to be highly induced in the host, consistent with prior reports of infection-dependent induction of pro-inflammatory and pro-fibrotic gene expression." (PMID 36923592, 2023). "Overexpression of XAF1 upregulated IRF1 protein levels in a dose-dependent manner in the HEK293T cells without any infection or stimulation, which further suggested that XAF1 regulates the turnover of the IRF1 protein." (PMID 35972291, 2022). "Infection with RNA viruses, including WSN, PR8, VSV, and SeV induced IRF1 expression." (PMID 35972291, 2022). "Infection with RNA viruses upregulates XAF1 expression by inducing its master TF IRF1, and the elevated XAF1 stabilizes the IRF1 protein to induce more antiviral IRF1 target genes." (PMID 35972291, 2022). "Reporter activity following infection with both viruses was decreased in ARHGEF3-expressing Huh7 cells although not to the same extent as the positive control IRF1." (PMID 36016278, 2022). "While control mice did not lose weight during the course of infection, Irf1–/–mice substantially lost weight, starting from day four post infection." (PMID 36175404, 2022).
infection (continued). "We next examined whether IRF1 expression was correlated with increased GCB frequency and decreased overall infection that we observed for the IFN-γ response in KSHV infected cultures." (PMID 36298850, 2022). "Mechanistically, infection with the bacterium, Francisella novicida, is sensed by the DNA sensor cyclic GMP-AMP synthase (cGAS)—stimulator of IFN genes (STING) pathway that activates type I IFN-dependent expression of IRF1." (PMID 33476326, 2021). "Our results are consistent with the hypothesis that restriction factors such as IRF1, MX1, STAT1, C18orf25 limit lytic infection." (PMID 33914843, 2021). "Using mRNA hybridization, we further show that uninfected bystander cells actively contribute to the resolution of infection by producing IL-6 and TNF-α, which, via paracrine signaling, activate IRF1/IRG1 and strengthen the antimicrobial activity of infected macrophages." (PMID 34607464, 2021). "In line with IFNRT, also KO of IRF9 again prevented the upregulation of IRF7 and also IRF2, but peculiarly, different from in the infection setting it did not lead to augmentation of IRF1 induction." (PMID 34685580, 2021). "Consistent with the microarray, protein levels of GBP2 and GBP5 were reduced in the Ifnar1−/−, Irf9−/−, Irf1−/−, Trif−/−, and Irf3−/−Irf7−/− macrophages that undergo extensive cell-cell fusion during infection but not in Myd88−/−." (PMID 32150572, 2020). "Antiviral activity towards PRRSV and the IBV/PRRSV coinfection displayed upregulation of interferon regulatory factors (IRFs) that included IRF1, IRF4, IRF8, expressed in the PRRSV infection and IRF7 showing up in place of IRF1 in the coinfection in this study." (PMID 33187194, 2020). "Moreover, the effect of IRF1 on the mediation of type III IFN induction upon CVB3 and PV1 infections was also evaluated." (PMID 33203755, 2020). "Similarly, the target genes of MERTK activation, the cytokine suppressors SOCS1 and SOCS3, were also increased after P strain infection, in addition to IRF-1, that regulates type I IFN levels, which were higher with C#1 compared with P strain infection." (PMID 31695702, 2019). "The luciferase reporter assay also showed significant suppression of the IRF1 promoter activity by wtCSFV infection (P < 0.001), but not by ∆Npro (P > 0.05)." (PMID 31683525, 2019). "IRF1-mediated restriction of VSV is IFN-independent, as blockade of types I and III IFNs and JAK-STAT signaling before infection did not affect VSV infection of either parent or IRF1 KO cells." (PMID 31156620, 2019). "Irf1 is an interferon regulatory factor and is logically induced during the infection, however its expression is not induced during the H1N1 infection." (PMID 28749409, 2017). "Thus, IFN-independent signaling should participate in the upregulation of PKR, especially during early infection (12 h p.i.)when PKR was statistically induced in contrast to IFN, IRF1, and IRF7." (PMID 29069722, 2017). "While IRF3 was partially implicated in S. suis-induced IFN-β by DCs, its expression was not modulated following infection with S. suis, unlike that of IRF1 and IRF7." (PMID 28894449, 2017). "In this study, we provide evidence that DENV/DENV-ADE infection of monocytes induces early production of ISG (NOS2) through the RIG-I/MDA-5-MAVS-NF-κB/IRF-1 signalling axis independent of the IFN pathway." (PMID 26923481, 2016). "At later times after infection, when discrete amounts of Tat are produced and available to amplify proviral transcription, IRF-1 becomes dispensable for proviral gene expression and is specifically targeted by Tat, resulting in IRF-1 inactivation (37, –, 39)." (PMID 27795392, 2016). "The distinct expression phenotypes exhibited by IRF1 and IRF8 following infection with FV1 lpg1− may be due to the difference in regulation of these two transcription factors." (PMID 26630499, 2015).
infection (continued). "Accordingly, the transcription factor IRF1, reported to be essential for MAVS-mediated IFNL1 expression, was detected in nuclear extracts as early as 6 h post infection with RSV-HD while it remained at basal levels in cells infected with RSV-LD or mock infected." (PMID 26336095, 2015). "IRF-1 mRNA expression did not change in the lung at any time point post infection, suggesting that it does not play a role in this tissue." (PMID 24675692, 2014). "We found that mice succumbed from VSV infection in the absence of IRF-1 only after neurotropic infections." (PMID 24675692, 2014). "In the cerebrum and cerebellum of IRF-1−/− mice, we observed a resurgence of IFN-β mRNA induction at day 6 post infection, which correlated to higher viral replication in the absence of IRF-1." (PMID 24675692, 2014). "We showed that in the absence of IRF-1 the majority of infected cells are neurons despite infection of some glia cells." (PMID 24675692, 2014). "Although, it is unknown how IRF-1 is induced in detail, STAT-1 was identified as an upstream inducer of IRF-1 in VSV and KSHV in vitro infection models." (PMID 24675692, 2014). "This was confirmed by infection experiments with IRF-1−/−NesCre+/−IFNARfl/fl mice which succumbed to infection significantly earlier than IRF-1+/− NesCre+/−IFNARfl/fl mice, indicating essential antiviral responses by IRF-1 that are overlooked due to the strong effects of type I IFN." (PMID 24675692, 2014). "Moreover, evidence was provided that the IRF-1, an IFN-γ-induced transcription factor pivotal in the regulation of infection and inflammation, upregulated TRAIL and DNAM-1/CD226 on NK cells." (PMID 23476104, 2013). "After three hours of infection, with IFNγ stimulation for the last two hours, cells pre-infected with either RH(I), Pru(II), or CEP(III) all had significantly lower levels of IRF1 in their nuclei than uninfected cells, as was previously seen for type I, II, and III strains." (PMID 23240025, 2012). "IRF1 was not inhibited as strongly in this infection as compared to the previous Western blot due to a lower MOI." (PMID 23240025, 2012). "In addition to our host model, two in vitro studies have previously reported the simultaneous activation of STATs, IRF-1, IRF-7, and Oct-1 after infection of human monocytes or dendritic cells by Mtb strains." (PMID 22675550, 2012). "Additionally, by 8 days after infection, the ratio of total wild type (CD45.1) to IRF-1-/- (CD45.2) CD8+ T cells continued to increase." (PMID 21909274, 2011). "However, neither MHV68 orf36 nor B cell-intrinsic IRF-1 expression altered Fas protein levels on the cell surface of germinal center B cells at 16 days post-infection." (PMID 41263556, 2025). "However, other authors have suggested that IRF1 may act as a key host cellular factor favoring HIV‐1 replication and early establishment of infection." (PMID 39998960, 2025). "Interestingly, infection with GNU-2353 and GNU-2377 significantly increased in IRF-1 expression, although not as high as that in response to VR-2332 infection." (PMID 40302751, 2025). "We conclude that the IRF1 functions in two modes- in absence of infection, ambient IRF1 mediates constitutive expression of the intrinsic IIR, whereas in response to RSV infection, the BRD4 CRC independently activates pSer2 Pol II to mediates robust expression of the intrinsic IIR." (PMID 38601157, 2024). "Notably, interferon regulatory factor-1 (IRF-1), which regulates the expression of interferon genes, and IFN-induced transmembrane (IFITM) mRNA expression showed a significant increase in BA.5, as compared to ancestral Wuhan-Hu-1, infection." (PMID 37704701, 2023). "The infection of neurons with the ZIKV induces IRG1, the enzyme that drives the synthesis of itaconate, by a complex Z-DNA binding protein (ZBP1)/receptor-interacting protein kinase 3 (RIPK3)/interferon regulatory factor 1(IRF1)-dependent mechanism, which, in turn restricts ZIKV replication." (PMID 37999239, 2023).